ZZEF1 (zinc finger ZZ-type and EF-hand domain containing 1)
Description:
Histone H3 reader which may act as a transcriptional coactivator for KLF6 and KLF9 transcription factors.
Synonyms: KIAA0399; ZZZ4; FLJ10821
Tractability: PROTAC: ubiquitination databases record sites on it; its protein half-life has been measured.
Gene: Protein-coding gene on chromosome 17 (4,004,445 to 4,143,628, reverse strand). Ensembl gene ENSG00000074755.
Subcellular location (Human Protein Atlas): Nucleoplasm; Mitochondria
Gene Ontology:
Molecular function: histone binding; protein binding; calcium ion binding; zinc ion binding
Genetic constraint (gnomAD): Loss-of-function variants: 153 observed, 338.42 expected, observed/expected ratio (o/e) 0.45, 90% interval 0.4 to 0.52. The upper end of that interval is the gene's LOEUF score, 0.52, which puts it in group 2 of 6, group 1 being the genes least tolerant of losing a copy. Missense variants: 3,472 observed, 3,808.8 expected, observed/expected ratio (o/e) 0.91, 90% interval 0.89 to 0.94. Synonymous variants: 1,504 observed, 1,465.4 expected, observed/expected ratio (o/e) 1.03, 90% interval 0.98 to 1.07.
Homologues: Orthologues: chimpanzee ZZEF1 (99% identical), macaque ZZEF1 (97% identical), pig ZZEF1 (92% identical), rat Zzef1 (91% identical), mouse Zzef1 (91% identical), guinea pig ZZEF1 (90% identical), rabbit ZZEF1 (89% identical), dog ZZEF1 (88% identical), tropical clawed frog zzef1 (63% identical), zebrafish zzef1 (59% identical).
Diseases named in the same sentence as ZZEF1 in open-access papers:
ZZEF1 is named in the same sentence as 6 diseases in open-access papers, as found by Europe PMC text mining. Sharing a sentence is not in itself a finding about the gene and the disease. The quoted sentences say what the papers report.
diabetes (2 papers, 2020 to 2024). "For the rest of the genes with associations only in the cohort with diabetes (ZZEF1 and Chol, ATXN7, PC, HLA-DQA1 and HDL), this study is the first to identify an association and more research will be required to establish a comprehensive understanding of their impact." (PMID 39258111, 2024).
cancer (4 papers, 2020 to 2024). A tumor composed of atypical neoplastic, often pleomorphic cells that invade other tissues. "Fusion genes are primarily known to be associated with cancer, and ZZEF1 has been found to create fusions with other genes in various cancers." (PMID 39436697, 2024). "Focusing on confirmed carcinomas (n = 11) we found four genes which were mutated in more than one sample: PIK3CA, KRAS, ZZEF1 and DOCK10 were each mutated in two of the carcinomas (18% each)." (PMID 36635367, 2023).
ZZEF1 also shares sentences with these, for which no sentence is quoted: colon cancer (2 papers); breast carcinoma (1); cardiovascular diseases (1); tumor (1).